TRRAP (transformation/transcription domain associated protein)
Description:
Adapter protein, which is found in various multiprotein chromatin complexes with histone acetyltransferase activity (HAT), which gives a specific tag for epigenetic transcription activation. Component of the NuA4 histone acetyltransferase complex which is responsible for acetylation of nucleosomal histones H4 and H2A. Plays a central role in MYC transcription activation, and also participates in cell transformation by MYC. Also involved in transcription activation mediated by the adenovirus E1A, a viral oncoprotein that deregulates transcription of key genes. Probably acts by linking transcription factors such as E1A, MYC or E2F1 to HAT complexes such as STAGA thereby allowing transcription activation. Probably not required in the steps following histone acetylation in processes of transcription activation. May be required for the mitotic checkpoint and normal cell cycle progression. Component of a SWR1-like complex that specifically mediates the removal of histone H2A.Z/H2AZ1 from the nucleosome. May play a role in the formation and maintenance of the auditory system (By similarity).
Synonyms: PAF350/400; PAF400; TR-AP; Tra1; DEDDFA; DFNA75; STAF40
Tractability: Small molecule: a structure with a bound ligand is known. PROTAC: UniProt records ubiquitination sites on it; ubiquitination databases record sites on it; its protein half-life has been measured.
Gene: Protein-coding gene on chromosome 7 (98,877,933 to 99,050,831, forward strand). Ensembl gene ENSG00000196367.
Subcellular location: Nucleus
Subcellular location (Human Protein Atlas): Nucleoplasm; Golgi apparatus
Pathways (Reactome):
Chromatin organization: HATs acetylate histones
Metabolism of proteins: Ub-specific processing proteases
Signal Transduction: Formation of the beta-catenin:TCF transactivating complex
Gene Ontology:
Molecular function: protein binding; transcription coregulator activity; kinase activity
Biological process: positive regulation of double-strand break repair via homologous recombination; regulation of cell cycle; regulation of transcription by RNA polymerase II; DNA repair-dependent chromatin remodeling; positive regulation of DNA-templated transcription; regulation of apoptotic process; regulation of DNA repair; regulation of DNA-templated transcription; regulation of double-strand break repair; regulation of RNA splicing; regulation of cellular response to stress
Cellular component: NuA4 histone acetyltransferase complex; nucleoplasm; nucleosome; nucleus; SAGA complex; Swr1 complex; transcription factor TFTC complex
Genetic constraint (gnomAD): Loss-of-function variants: 38 observed, 433.11 expected, observed/expected ratio (o/e) 0.0877, 90% interval 0.067 to 0.12. The upper end of that interval is the gene's LOEUF score, 0.12, which puts it in group 1 of 6, group 1 being the genes least tolerant of losing a copy. Missense variants: 3,086 observed, 5,155.7 expected, observed/expected ratio (o/e) 0.6, 90% interval 0.58 to 0.62. Synonymous variants: 1,964 observed, 2,015.7 expected, observed/expected ratio (o/e) 0.97, 90% interval 0.94 to 1.01.
Gene-disease validity (ClinGen):
ClinGen rates the evidence that TRRAP causes each of these diseases.
complex neurodevelopmental disorder with or without congenital anomalies (autosomal dominant): Definitive. A complex neurodevelopmental disorder that involves more than one phenotype associated with the central nervous system, including but not limited to intellectual disability, autism, and seizures (epilepsy), in addition to one or more structural or functional anomaly(ies) that develops prenatally.
Cancer hallmarks: proliferative signalling (promotes); escaping programmed cell death (promotes); genome instability and mutations (suppresses); escaping programmed cell death
Homologues: Orthologues: macaque TRRAP (99% identical), dog TRRAP (99% identical), chimpanzee TRRAP (99% identical), pig TRRAP (99% identical), rat Trrap (99% identical), guinea pig TRRAP (99% identical), mouse Trrap (98% identical), rabbit TRRAP (98% identical), tropical clawed frog trrap (94% identical), zebrafish trrap (92% identical), Drosophila melanogaster Nipped-A (52% identical). Paralogues in human: PRKDC (13% identical), ATM (10% identical), ATR (10% identical), SMG1 (8% identical), MTOR (8% identical).
Diseases named in the same sentence as TRRAP in open-access papers:
TRRAP is named in the same sentence as 59 diseases in open-access papers, as found by Europe PMC text mining. Sharing a sentence is not in itself a finding about the gene and the disease. The quoted sentences say what the papers report.
melanoma (7 papers, 2013 to 2026). A malignant, usually aggressive tumor composed of atypical, neoplastic melanocytes. "A number of mutations, including the prevalent melanoma mutation S722F (TRRAP isoform here, S721F), are part of a highly conserved surface patch and probably involved in effector binding." (PMID 34811519, 2021). "Interestingly, a mutation in TRRAP has recently been associated with human melanoma that together with its interaction with MITF suggests a role in melanomagenesis." (PMID 25803486, 2015). "Chromosome 7, with frequent copy number gains in all four cancers, harbors several key oncogenes such as EGFR, CDK6, and MET in glioma; KMT2C and PMS2 in medulloblastoma; BRAF, RAC1, and TRRAP in melanoma." (PMID 41537310, 2026). "As expected, this list included well documented frequent oncogenic drivers of melanoma, including hotspot mutations in BRAF, NRAS, RAC1, PPP6C, TRRAP, MAP3K5 and BCL2L12." (PMID 24913145, 2014). "Exon 1 of the TRRAP gene and exons 1, 2, 3, 4 and 5 of the GRM3 gene were analyzed as these exons have also been reported to harbor somatic mutations in melanoma." (PMID 24137342, 2013). "None of the melanomas harbored the hotspot activating mutation p.S722F in TRRAP, although we identified one sample with another TRRAP pathogenic variant (p.P814S)." (PMID 28356599, 2017).
breast carcinoma (6 papers, 2021 to 2025). "TRRAP expression levels have been reported to be significantly upregulated in breast cancer, while the TRRAP knockdown reduced the CSC-like properties of glioma." (PMID 37047234, 2023). "In addition, a putative tumor-suppressive role of TRRAP has been described in breast carcinomas where TRRAP is significantly downregulated compared to normal breast tissues, and lower TRRAP expression correlates with a shorter survival time." (PMID 33937075, 2021). "Predictions of known cancer driver genes in new cancer types include SPTA1, CHD4 and ASXL1 in colorectal cancer, FOXO3, MUC16 and ZFPM1 in breast cancers and CNTNAP2, CTNND2 and TRRAP in lung adenocarcinoma." (PMID 38890488, 2024).
cholangiocarcinoma (4 papers, 2021 to 2023). A carcinoma that arises from the intrahepatic biliary tree (intrahepatic cholangiocarcinoma) or from the junction, or adjacent to the junction, of the right and left hepatic ducts (hilar cholangiocarcinoma). "Three tumor antigens, such as CD247, FCGR1A, and TRRAP, correlated with superior prognoses and infiltration of antigen-presenting cells were identified in cholangiocarcinoma." (PMID 33685460, 2021). "CD247, FCGR1A, and TRRAP are potential antigens for mRNA vaccine development against cholangiocarcinoma, specifically for patients with IS2 tumors." (PMID 33685460, 2021).
Intellectual disability (4 papers, 2021 to 2026). "TRRAP pathogenic missense variants were associated with developmental delay (DD), intellectual disability (ID), autistic spectrum disorder (ASD), and cranio‐facial features (MIM#618454)." (PMID 40583039, 2026). "TRRAP pathogenic variants were linked to neurodevelopmental disorders, intellectual disability, congenital anomalies, and hearing loss." (PMID 40583039, 2026). "The mutations of TRRAP are recently associated with multiple abnormalities and characterized by intellectual disability or autism spectrum disorders." (PMID 40725218, 2025). "Among the three disease-causing genotypes identified in Patients 1–3, the LPV of TRRAP p.(Ala1043Thr), identified in Patient 3, is the only genotype previously reported in five individuals with syndromic intellectual disability (ID) with malformations." (PMID 38909058, 2024). "Mutations of HAT cofactor TRRAP (transformation/transcription domain-associated protein) cause human neuropathies, including psychosis, intellectual disability, autism, and epilepsy, with unknown mechanism." (PMID 33594975, 2021).
schizophrenia (4 papers, 2016 to 2026). A major psychotic disorder characterized by abnormalities in the perception or expression of reality. "TRRAP protein is vital to early neural developmental processes, and variants in this gene have been associated with schizophrenia and childhood disintegrative disorder." (PMID 30424743, 2018). "TRRAP is found mutated in patients with schizophrenia and controls the tumourigenicity of brain tumour initiating cells which resemble neural stem cells." (PMID 27782803, 2016). "Notably, rare TRRAP mutations were found in some patients with schizophrenia, ID, and ASD." (PMID 35743796, 2022). "TRRAP missense variants were associated also with neuropsychiatric disorders other than ASD, such as schizophrenia and childhood disintegrative disorder." (PMID 40583039, 2026). "The same research group also showed that TRRAP was one of four genes (LAMA2, DPYD, TRRAP and VPS39) that were affected by de novo variants a significant number of times in a sample population of 231 subjects with schizophrenia." (PMID 30424743, 2018).
autism (3 papers, 2021 to 2026). Persistent deficits in social interaction and communication and interaction as well as a markedly restricted repertoire of activity and interest as well as repetitive patterns of behavior. "TRRAP pathogenic missense variants determine AD pleiotropic neurodevelopmental syndrome with or without peculiar facies and autism (MIM#618454)." (PMID 40583039, 2026). "The WES approach allowed us to identify five clinically relevant variants in the GZF1, NFIX, TRRAP, FGFR2 and PAX2 genes associated with Larsen, Malan, developmental delay with or without dysmorphic facies and autism, LADD1 and papillorenal syndromes." (PMID 38909058, 2024).
colorectal cancer (3 papers, 2022 to 2024). A primary or metastatic malignant neoplasm that affects the colon or rectum. "Using CRISPR-Cas9 genome editing, we fused an auxin-inducible degron (AID) to the endogenous TELO2 or TRRAP proteins in human HCT116 colorectal cancer cells (CRCs)." (PMID 35244540, 2022). "Here, using endogenous auxin-inducible degron alleles, we show that the TTT subunit TELO2 promotes TRRAP assembly into SAGA and TIP60 in human colorectal cancer cells (CRCs)." (PMID 35244540, 2022).
lymphoma (3 papers, 2022 to 2024). A malignant (clonal) proliferation of B- lymphocytes or T- lymphocytes which involves the lymph nodes, bone marrow and/or extranodal sites.
ovarian carcinoma (3 papers, 2021 to 2023). A malignant neoplasm originating from the surface ovarian epithelium. "TRRAP overexpression also increased the mRNA levels of NANOG, while TRRAP knockdown reduced tumor growth in a murine ovarian cancer xenograft model." (PMID 37047234, 2023). "TRRAP expression is upregulated in spheroid cultures of A2780 ovarian cancer cells." (PMID 37047234, 2023). "In addition, TRRAP depletion leads to down‐regulation of TOP2A, which is consistent with our results and indicates that the association between these two genes is worthy of exploration in ovarian cancer." (PMID 35735060, 2022). "Furthermore, TRRAP is a component of a coactivator complex with HAT activity that is required for the transactivation function of the tumor suppressor BRCA1, which is frequently mutated at the onset of breast and ovarian cancer in women." (PMID 33937075, 2021).
prostate carcinoma (3 papers, 2012 to 2022). A carcinoma that arises from epithelial cells of the prostate gland. "For instance, the TRRAP gene, involved in transcriptional regulation and DNA repair, was found to be high in bone metastases from prostate cancer, intermediate in BC, and low in lung and kidney cancers." (PMID 23343470, 2013). "Here, we demonstrate that replicating mutants deleted in small E1A-domains, binding pRb (dl1108), p300/CBP (dl1104) and p400/TRRAP or p21 (dl1102) sensitize human prostate cancer cells (PC-3, DU145, 22Rv1) to mitoxantrone and docetaxel." (PMID 23056370, 2012).
psychosis (3 papers, 2018 to 2026). "A de novo TRRAP missense variant was identified in a patient with very early onset psychosis, nonverbal learning disability, and history of obsessive‐compulsive disorder." (PMID 40583039, 2026).
Ataxia (2 papers, 2015 to 2021). Ataxia refers to impaired coordination of voluntary muscle movement. "TRA1 is a representative of a group of proteins that include DNA-dependent protein kinase catalytic subunit, ATM (Ataxia telangiectasia mutated) and TRRAP (transformation/transcription domain-associated protein), with the carboxyl-terminal regions related to phosphatidylinositol 3-kinases." (PMID 26263547, 2015).
colon adenocarcinoma (2 papers, 2022 to 2023). "In the present study, we demonstrated increased TRRAP expression in HCT-15 colon adenocarcinoma spheroids." (PMID 37047234, 2023). "We revealed the colon adenocarcinoma patients (COAD) with mutations of a CRs set (EP300, MSH6, NSD2 and TRRAP) mediate a better survival with low expression of MAP2 and could benefit from taxnes." (PMID 36180906, 2022).
colon cancer (2 papers, 2022 to 2023). "The present study provides the first evidence that TRRAP plays an important role in the tumorigenic ability of colon cancer cells by regulating NANOG protein stability." (PMID 37047234, 2023). "Together, these results suggest that TRRAP plays a pivotal role in the regulation of the tumorigenic potential of colon cancer cells by modulating NANOG protein stability." (PMID 37047234, 2023). "Taken together, these results suggest that TRRAP may be a key target gene for colon cancer treatment." (PMID 37047234, 2023). "To clarify the role of TRRAP in colorectal CSCs, we measured the expression levels of TRRAP and NANOG in adherent and three-dimensional spheroid cultures of HCT-15 colon cancer cells." (PMID 37047234, 2023).
developmental delay (2 papers, 2021 to 2024). "In one study, most of the 13 patients with TRRAP variants in the codon 1031–1159 region (the cluster of human TRRAP mutations) had global developmental delay with craniofacial abnormalities." (PMID 34934055, 2021). "Recently, it has been reported that human patients with genetic mutations in the TRRAP gene show various symptoms, including facial dysmorphisms, microcephaly and global developmental delay." (PMID 34934055, 2021). "Recent accumulating evidence demonstrates that human patients with genetic mutations in the TRRAP gene have various symptoms, including facial dysmorphisms, microcephaly, global developmental delay and intellectual disability." (PMID 34934055, 2021).
osteosarcoma (2 papers, 2020 to 2026). A usually aggressive malignant bone-forming mesenchymal neoplasm, predominantly affecting adolescents and young adults. "In a recent kinome‐wide CRISPR‐Cas9 library study, high expression of TRRAP in normal bone tissue and osteosarcoma cellular lines was demonstrated." (PMID 40583039, 2026). "We further validated that TRRAP, PKMYT1, and TP53RK are required for osteosarcoma cell proliferation and colony formation." (PMID 32944406, 2020). "Among these targets, we analyzed 3 kinases, TRRAP, PKMYT1, and TP53RK, to validate their oncogenic functions in osteosarcoma." (PMID 32944406, 2020). "Consequently, we decided to validate whether the 3 other hits from our screening, TRRAP, PKMYT1, and TP53RK, were truly essential in osteosarcoma cell lines, given that their functions in osteosarcoma remain unknown." (PMID 32944406, 2020).
colon adenoma (1 paper, 2017). An adenoma that arises from the colon.
colorectal tumours (1 paper, 2010). "MRG-binding protein (MRGBP) or C20orf20, encoding a subunit of TRRAP/TIP60-containing histone acetyltransferase complex, was up-regulated in the majority of colorectal tumours." (PMID 20051959, 2010).
COVID-19 (1 paper, 2024). A disease caused by infection with severe acute respiratory syndrome coronavirus 2. "In accordance with the PPI analyses, we found that the V-ATPase subunit ATP6V1B2, the c-MYC co-activator TRRAP, and the cohesin complex subunit SMC3 were associated with the COVID-19 patient hospitalization, suggesting their clinical relevance to disease." (PMID 38168026, 2024).
cyst (1 paper, 2023). A sac-like closed membranous structure that may be empty or contain fluid or amorphous material. "Interestingly Tor is activated in CBs, but nucleolar volume reduction is only apparent from the 2-cell cyst stage onward, which may be explained by the rapid action of the Tor kinase compared with TRRAP, which is a transcriptional regulator." (PMID 36870055, 2023).
deafness (1 paper, 2020). An inherited or acquired condition characterized by the complete loss of the ability to hear from one or both ears. "Two other genes, Transformation/Transcription Domain Associated Protein (TRRAP) and Potassium Inwardly Rectifying Channel Subfamily J Member 10 (KCNJ10), have been associated with deafness in humans." (PMID 32413090, 2020).
glioblastoma (1 paper, 2025). The most malignant astrocytic tumor (WHO grade IV). "Its role in glioblastoma extends beyond transcription to influencing immune interactions, marking TRRAP as a novel effector in GBM pathogenesis." (PMID 41179304, 2025).
hepatocellular carcinoma (1 paper, 2022). A malignant tumor that arises from hepatocytes. "KAT5/transformation/transcription domain-associated protein (TRRAP) exerted a role in promoting hepatocellular carcinoma cell proliferation by activating mitotic genes." (PMID 35383533, 2022).